BRAF (B-Raf proto-oncogene, serine/threonine kinase)
Diseases named in the same sentence as BRAF in open-access papers (continued):
Sharing a sentence is not in itself a finding about the gene and the disease.
melanoma (continued). "UVR remains the primary environmental driver of melanoma, inducing direct DNA damage (e.g., BRAF mutations), generating ROS, and promoting immunosuppression." (PMID 41085102, 2025). "Therapeutic strategies combining BRAF inhibitors with agents targeting eIF4F have demonstrated the ability to overcome most resistance pathways that emerge in cancers carrying the BRAF (V600) mutation such as melanoma, colon and thyroid cancers." (PMID 41208200, 2025). "Melanoma cells with BRAF mutation exhibit a significant alteration in their energy metabolism, particularly through an increase in aerobic glycolysis (Warburg effect)." (PMID 40872623, 2025). "We observed elevated SPACA6 expression levels in melanoma tumors that progressed during BRAF/MEKi therapy, an increase associated to the upregulation of the hosted miR-99b∼125a∼let-7e cluster." (PMID 41550951, 2025). "Mutations in BRAF, the most important driver of cutaneous melanoma, are present in 40–50% of melanoma patients." (PMID 39968494, 2025). "The most abundant mutation is BRAFV600E, which represents approximately 90% of all BRAFV600 mutations (which represent about 90% of all BRAF mutations) in melanoma and fosters tumor proliferation, survival, invasiveness, and drug resistance." (PMID 39935431, 2025). "For instance, patients with unresectable stage IIIC or IV melanoma harbouring a BRAF V600E/K mutation can benefit from combination therapies targeting both BRAF and MEK." (PMID 41017066, 2025). "Collectively, these results indicate that ArcA exhibits potent cancer-specific cytotoxic effects, with enhanced efficacy in BRAF-mutated melanoma cells." (PMID 39948552, 2025). "Recently, TIMP-2 has been implicated in the mechanism of resistance to BRAF inhibitors in melanoma cells." (PMID 40869222, 2025). "European guidelines recommend mutation testing—particularly for BRAF V600—in advanced melanoma to guide personalized therapy." (PMID 41375623, 2025). "Approximately half of all melanoma patients harbor mutations of the proto-oncogene BRAF encoding a serine/threonine protein kinase in the RAS-RAF-MEK-ERK kinase pathway, which in turn promotes cell growth and proliferation." (PMID 40918526, 2025). "As melanoma is frequently associated with oncogenic aberrations with BRAF mutations, drug development in the field of targeted therapies has arisen, first with the use of BRAF inhibitor (BRAFi) monotherapy (vemurafenib) in BRAF-mutated melanoma." (PMID 40027067, 2025). "Trm initially was used to treat BRAF V600E-mutated melanoma but its FDA-approved indications are expanding rapidly." (PMID 40964318, 2025). "Conversely to WT melanomas, those harboring a mutation in BRAF, NRAS, or cell cycle reported clinical and dermoscopic features underlying a more aggressive phenotype." (PMID 40867317, 2025). "BRAF-mutant melanomas tend to be immunologically “hot”, especially when associated with high tumor mutational burden (TMB)." (PMID 41465101, 2025). "The BRAF V600E mutation, a common oncogenic driver of melanoma, constitutively activates the MAPK signaling pathway, leading to uncontrolled cellular proliferation and survival." (PMID 39984334, 2025). "Melanoma is classically driven by mutations in genes such as BRAF, NRAS, and c-KIT, which promote uncontrolled cell growth and survival." (PMID 40725203, 2025). "For example, enforced ERK expression in melanoma cells carrying an activating mutation in BRAF (BRAFV600E) triggered cell death in vitro and tumor regression in xenograft models." (PMID 41155983, 2025). "A higher burden of BRAF mutations leads to accelerated melanoma development, with copy number alterations being associated with lethal development." (PMID 39794352, 2025). "Wild-type IRF-8 and the K250R mutant, a ubiquitination-defective variant, were overexpressed in BRAF-mutant melanoma cell lines." (PMID 41315179, 2025).
melanoma (continued). "In particular, the authors showed, in various in vitro models of altBRAF-driven melanoma resistance, that altBRAFs are produced exclusively from the BRAF V600E allele and are associated with corresponding genomic deletions." (PMID 40872623, 2025). "Activating BRAF mutations, primarily at codon 600 with V600E as the most prevalent change, are found in about 40–60% of melanomas." (PMID 39859576, 2025). "The evasion of apoptosis induction is a hallmark of BRAF inhibitor-resistant BRAF-mutant melanoma, and epigenetic mechanisms play a vital role in the prevention of cell death during BRAF inhibitor therapy." (PMID 39935431, 2025). "For example, in melanoma, the BRAF V600E mutation results in constitutive activation of the MAPK pathway, promoting uncontrolled cell growth." (PMID 40510029, 2025). "In the history of melanoma treatment, substantial strides have been achieved with targeted therapy, particularly benefiting the largest group of patients with BRAF mutations." (PMID 40473796, 2025). "Patients with BRAF-mutated melanomas and brain metastases have a lower overall survival compared to patients with BRAFWT melanomas and brain metastases." (PMID 41010758, 2025). "Typically, BRAF mutations are linked to melanomas detected in young individuals and areas intermittently exposed to sunlight." (PMID 41142596, 2025). "If the melanoma is BRAF V600E mutation positive, then kinase inhibitors such as dabrafenib/trametinib, vemurafenib/cobimetinib, and encorafenib/binimetinib are preferred." (PMID 40621305, 2025). "Adjuvant BRAF-targeted therapy for the same duration was permitted for patients with melanoma harboring a BRAF V600 mutation." (PMID 40857557, 2025). "Efforts to elucidate the molecular hallmarks of melanoma have long focused on canonical mutations in genes such as BRAF and NRAS." (PMID 40607411, 2025). "This pattern is similar to our previous observations in melanoma and glioblastoma, where the highest sensitivity to ML was seen in melanoma cells, particularly those with BRAF mutations." (PMID 40004697, 2025). "In one study that included only eight patients with BRAF V600E/K-mutated melanoma, ctDNA was quantified in CSF using ddPCR." (PMID 39859576, 2025). "Exploratory analysis of prognostic factors impacting the OS was performed for ECOG, melanoma primary location, melanoma type, BRAF mutation status, M stage according to AJCC seventh edition, number of affected organs, LDH levels, and 1L treatment type." (PMID 40027067, 2025). "Consensus was also achieved for statement 9, which proposes BRAF-targeted therapy as an alternative neoadjuvant treatment for resectable stage IIIA-IIID melanoma harboring a BRAF V600 mutation for whom ICI therapy is contra-indicated." (PMID 40857557, 2025). "The genomic landscape of melanoma features numerous genomic alterations with key driver mutations in genes, such as BRAF (45%), NRAS (17%), and KIT (9%), leading to dysregulated cell growth and survival pathways." (PMID 40004220, 2025). "The combined treatment with PTX loaded into chitosan NBs decorated with ICOS-Fc displays a substantial anti-melanoma effect in vivo against a highly aggressive BRAF-mutated tumor." (PMID 41471045, 2025). "Resistance to targeted therapies poses a significant challenge in advanced melanoma with BRAF mutations." (PMID 40592836, 2025). "For example, while BRAF inhibitors revolutionized treatment for BRAF-mutated melanoma, resistance frequently occurs, limiting long-term efficacy." (PMID 41008880, 2025). "Another interesting study highlights significant differences in mitochondrial function and immune responses between BRAF V600E-mutated and wildtype melanoma samples through proteomic analysis." (PMID 40565936, 2025).
melanoma (continued). "BRAF and MEK inhibitor combinations (BRAF/MEKi) have significantly improved survival in melanoma patients with BRAF mutations, but can induce a wide spectrum of cardiovascular (CV) toxicities." (PMID 40507236, 2025). "Approximately half of melanomas harbor the v-Raf murine sarcoma viral oncogene homolog B (BRAF) mutation, a pivotal driver gene in the mitogen-activated protein kinase (MAPK) signaling pathway." (PMID 40617808, 2025). "BRAF mutations occur in approximately 60% of melanomas, 60% of thyroid cancers, 15% of colorectal cancers, and 5–8% of non-small cell lung cancers." (PMID 40363930, 2025). "In a previous meta-analysis, the associated risk of pulmonary embolism was higher for melanoma patients treated with BRAF/MEKi (2.2%) compared with BRAFi monotherapy (0.4%)." (PMID 40507236, 2025). "In all types of melanoma, BRAF-mutated tumors have been reported to be more aggressive than the corresponding wild-type tumors." (PMID 40320509, 2025). "Downregulation of ERRFI1 with the help of siRNA increased the susceptibility of melanoma cells toward BRAF inhibition (BRAFi) and resensitized BRAFi-resistant melanoma cells to BRAFi." (PMID 41044875, 2025). "In conclusion, this study significantly enhances our understanding of the molecular mechanisms underlying BRAF-driven melanoma progression by elucidating the TRIM63/IRF-8 axis." (PMID 41315179, 2025). "Specifically, MitoTracer was tested on a Fluidigm scRNA-Seq dataset of 451Lu melanoma cells harboring the BRAF V600E mutation." (PMID 40549685, 2025). "It has been reported that USP18 enhances the resistance of BRAF-mutated melanoma cells to vemurafenib by stabilising cGAS expression and inducing autophagy." (PMID 40374599, 2025). "Meanwhile, BRAF mutants, such as V600E, represent a prominent mutation observed in melanoma patients, yet the underlying mechanism remains elusive." (PMID 41315179, 2025). "The BRAF oncogene mutation was initially described in melanoma, and subsequent studies identified the mutation in melanocytic nevi." (PMID 41202496, 2025). "Binimetinib is an anticancer drug used in combination therapy for malignant melanoma with a V600 mutation in the BRAF gene." (PMID 41373567, 2025). "BRAF mutation was detected in 47.6% of the 84 patients with stage III or IV melanoma that underwent this molecular analysis." (PMID 40994966, 2025). "Small-molecule inhibitors such as Dabrafenib and Vemurafenib, which selectively target BRAF^V600E mutations, are now standard of care for a majority of melanoma patients, whereas those harboring KIT mutations benefit from Imatinib7." (PMID 41279995, 2025). "BRAF-mutated melanomas are generally more aggressive in stage IV disease and are associated with reduced survival." (PMID 40981345, 2025). "The only combination therapy that doesn’t target angiogenesis directly is given in BRAF-mutated advanced melanoma, i.e., a combination of Vemurafenib (a BRAF inhibitor), cobimetinib (a mitogen-activated extracellular kinase (MEK) inhibitor), and atezolizumab." (PMID 40584631, 2025). "Differently from the hyperfused phenotype observed in melanoma cells with a BRAF mutation, SK-MEL-147 cells incubated with vemurafenib exhibited smaller, rounded mitochondria, similar to the control, suggesting mitochondrial fission prevalence." (PMID 40141318, 2025). "BRAF V600E mutations are present in about half of melanomas and have been successfully targeted with BRAF inhibitors in melanomas, such as dabrafenib." (PMID 41367868, 2025). "In BRAF V600E mutated melanoma, where activation of the MAPK pathway is due to the mutated BRAF protein only, treatment with a MEKi does not lead to reactivation of MEK through CRAF." (PMID 41199020, 2025). "More specifically, the BRAF mutation is quite common in these cancers as well, accounting for 30% of ovarian tumors, 40% of papillary thyroid cancers, 50–70% of melanomas, and nearly 100% of hairy cell leukemias." (PMID 40943615, 2025).
melanoma (continued). "Of patients with stage III/IV BRAF-mutated melanoma who received systemic anticancer therapy, 59% (n = 784/1338) received targeted therapy as the first-line treatment." (PMID 40902091, 2025). "Since the BRAF V600E mutation is the most common and significant pathogenic alteration in melanoma, efforts in this cancer have primarily been directed at detecting the V600E mutation in ctDNA." (PMID 39859576, 2025). "Approximately 48% of melanoma cases harbor a BRAF mutation, with the BRAF V600E mutation being particularly prevalent." (PMID 40191195, 2025). "Patients with BRAF V600 mutation-positive melanoma are eligible for treatment with FDA-approved BRAF inhibitors, though the current standard of care is immunotherapy." (PMID 40399445, 2025). "The association between BRAF mutations and lower survival, particularly for stage II melanoma, underscores the importance of incorporating BRAF testing into early-stage melanoma care." (PMID 40902091, 2025). "Currently, the combination of BRAF and MEK inhibitors is the standard of care in BRAF V600E-mutated melanomas with three FDA approvals." (PMID 40111124, 2025). "Melanoma and BRAF/MEK inhibitors are important because about half of melanomas mutate in the BRAF gene (V600E)." (PMID 40647400, 2025). "Genetically engineered mouse models (GEMMs) are practical tools for modeling human cancer, and several studies have been conducted to identify the genetic changes related to BRAF-mutated melanoma using GEMMs8." (PMID 39794352, 2025). "Results from the DREAMSeq clinical trial determined that the best improvements in PFS and OS were in BRAF V600 mutation-positive melanoma patients receiving a combination of BRAF and MEK inhibitors (dabrafenib/trametinib)." (PMID 40399445, 2025). "BRAF mutations, particularly the V600E variant, are present in approximately 40-60% of melanomas and are most frequently observed in SSM, especially those arising on intermittently sun-exposed skin." (PMID 40984902, 2025). "(2012) identified BRAF mutations in 50% of melanomas, NRAS mutations in 30%, NF1 mutations in 12–23%, and PTEN mutations in 5–40%, highlighting their role in melanoma progression and therapeutic responsiveness." (PMID 41142596, 2025). "Its role in modulating PD-L1 expression in cancer cells was initially suggested by the observation that the treatment of melanoma cells with a BRAF inhibitor causes a reduction in PD-L1 levels." (PMID 40941018, 2025). "A phase III trial with patients with BRAF-mutated melanoma showed a significant prolongation of overall survival if treated with Trametinib, a Mitogen-activated protein kinase kinase (MEK) inhibitor, together with Dabrafenib, a BRAF inhibitor." (PMID 41299419, 2025). "More specifically, over 50% of patients with advanced melanoma harbor activating mutations in the BRAF oncogene." (PMID 41284701, 2025). "Melanomas, while typically benign in cutaneous forms, exhibit aggressive behavior in oral and digital locations, with BRAF and NRAS mutations playing an integral role in tumor growth." (PMID 41394861, 2025). "Binimetinib is predominantly employed to treat melanoma caused by the genetic mutation BRAF (V-raf murine sarcoma viral oncogene homolog B1)." (PMID 41155569, 2025). "Approximately 85% of melanomas harbor primary pathogenic alterations in key genes such as BRAF, NRAS, NF1 or KIT, which include mutations, deletions or amplifications." (PMID 39859576, 2025). "Approximately 40–60% of cutaneous melanomas harbor BRAF mutations—predominantly the V600E variant—which constitutively activates MAPK signaling, promoting tumor proliferation and survival." (PMID 41302945, 2025). "Mutations of this cascade are highly prevalent in human cancer, and the isoform of RAF known as BRAF is implicated in as many as 60% of melanomas." (PMID 40564107, 2025). "The higher count of melanocytic naevi and sun exposure in early life increases the risk of developing a BRAF-mutant melanoma." (PMID 41010758, 2025).
melanoma (continued). "In cancers such as melanoma that are more prone to BRAF mutations, ICIs such as vemurafenib and dabrafenib target the pathway to decrease cancer spread." (PMID 39857950, 2025). "The observed sensitivity of BRAF V600E-mutated melanoma cells to LA, particularly in the Malme-3M cell line, underscored its potential therapeutic applicability." (PMID 39795195, 2025). "BRAF mutations are present in approximately 40–60% of all melanomas, with BRAFV600E being the most frequent, but there are percentage differences between different studies according to the population studied or the detection method used." (PMID 41010758, 2025). "In this retrospective study, we compared the efficacy of 1 year versus extended adjuvant therapy with dabrafenib combined with trametinib in Chinese patients from six centers diagnosed with Stage III malignant melanoma harboring BRAF mutations." (PMID 40366077, 2025). "Unfortunately, therapies targeting BRAF mutations in melanoma or KRAS mutations have shown limited efficacy in patients with NRAS-mutated tumors." (PMID 39940799, 2025). "BRAF inhibitors, which target V600 variants, have been approved for several other malignancies including melanoma and non-small cell lung carcinoma." (PMID 40270074, 2025). "A hallmark of many cancers, including BRAF mutant melanoma, is their strong reliance on aerobic glycolysis to meet the energy demands of rapid growth and proliferation." (PMID 41155949, 2025). "BRAF mutations were detected in up to 60% (3/5) of cervical or vaginal melanoma patients, which is inconsistent with the reported 10% activation of BRAF mutations in mucosal melanoma cases." (PMID 40933889, 2025). "It is often observed that melanoma with BRAF mutations develops resistance to BRAF inhibitor treatments." (PMID 41155168, 2025). "Advanced-stage melanoma had the highest odds of being BRAF mutated [stage III OR 1.61 (95% CI 1.46–1.78); stage IV OR 1.47 (95% CI 1.27–1.70)]." (PMID 40902091, 2025). "Even molecular testing to determine BRAF mutation status is now a standard of care for patients with advanced melanoma." (PMID 40361518, 2025). "In superficially spreading melanomas, a characteristic anamnestic finding is a high incidence of nevi and intermittent UV exposure; also, the presence of the BRAF V600E mutation is common in this histological type." (PMID 40361349, 2025). "Treatment for metastatic melanoma is determined by the number of metastases, location, and size of metastases, prior treatment for melanoma, presence of a BRAF mutation, presence of extracranial metastases, and the patient’s current performance status." (PMID 40585739, 2025). "Of patients with BRAF-mutated melanoma, those who received first-line immunotherapy had higher disease-specific survival; however, limitations of the data included difficulty identifying treatment intent, recurrence and treatment windows." (PMID 40902091, 2025). "The mutation of BRAF, a proto‐oncogene, particularly the V600E mutation, is responsible for 40%–60% of melanoma cases and is associated with sun exposure and genomic instability." (PMID 40761498, 2025). "When including other mitogen-activated protein kinase (MAPK) pathway mutations, peppering was observed to be more frequent in BRAF- or NRAS-mutated melanomas." (PMID 41010758, 2025). "Melanomas harboring BRAF V600E mutations, when treated with BRAF inhibitors, frequently undergo metabolic rewiring that increases glycolysis and HK II/PKM2 dependency." (PMID 41614770, 2025). "Vertical pathway inhibition has been well established in overcoming resistance to single-agent BRAF inhibitors in melanoma harboring BRAF V600 mutations and thus driving deeper and more durable responses." (PMID 40111124, 2025). "BRAF mutations are present in approximately 40%-50% of melanomas, and these mutations lead to constitutional activation of the MAP-K/EPK signaling pathway, which promotes cell proliferation and survival." (PMID 39974235, 2025).